ANKLE1 (ankyrin repeat and LEM domain containing 1)
Diseases named in the same sentence as ANKLE1 in open-access papers:
ANKLE1 is named in the same sentence as 19 diseases in open-access papers, as found by Europe PMC text mining. Sharing a sentence is not in itself a finding about the gene and the disease. The quoted sentences say what the papers report.
breast carcinoma (17 papers, 2016 to 2025). "Taken together these integrative genomics analyses suggest that susceptibility to breast cancer, ANKLE1 expression, and mtDNA-CN phenotypes share common causal genetic variant(s) within the chr19p13.1 region." (PMID 36859531, 2023). "Modern genomics and phenotyping can convincingly identify genes that affect a phenotype, in this case ANKLE1 and breast cancer risk." (PMID 36859531, 2023). "We also explore the undesired role that ectopic expression of ANKLE1 plays in conferring breast cancer risk." (PMID 36859531, 2023). "We propose that breast cancer risk variants directly regulate ANKLE1 expression in breast tissue, which directly leads to mtDNA degradation and results in modified cellular metabolism and homeostasis." (PMID 36859531, 2023). "Alleles such as rs67397200, which affect ANKLE1 expression and contribute to breast cancer risk are common and found at 25% minor allele frequencies." (PMID 36859531, 2023). "Ankyrin repeat and LEM-domain containing protein 1 (ANKLE1) cleaves the mitochondrial genome during erythropoiesis and ectopic expression of ANKLE1 promotes genome instability and apoptotic resistance, which contributes to breast cancer risk." (PMID 36859531, 2023). "Genome-wide association data and expression QTL data suggest common causal variant(s) within the chr19p13.1 locus for breast cancer risk, ANKLE1 expression, and mtDNA copy number." (PMID 36859531, 2023). "Variants in the chr19p13.1 locus both increase ANKLE1 expression and the risk of developing breast cancer." (PMID 36859531, 2023). "Alleles within the chr19p13.1 locus are associated with increased risk of both ovarian and breast cancer and increased expression of the ANKLE1 gene." (PMID 36859531, 2023). "ANKLE1 was known as a new hotspot for the predisposition of breast cancer, which played a vital role in DNA damage response and DNA repair." (PMID 35464857, 2022). "Whole Exome Sequencing (WES) of paired breast cancer samples was performed and ANKLE1 was found to be a new possible hotspot for predisposition of breast cancer." (PMID 33584808, 2020). "Here we report the detailed studies on WES and mass array genotypic of variant rs2363956 and observed that genetic variations in ANKLE1 is associated with breast cancer population in India." (PMID 33584808, 2020). "The mass array genotyping for breast cancer variant rs2363956 further confirmed the ANKLE1 association with the studied population of breast cancer." (PMID 33584808, 2020). "We identified two SNPs out of six total eQTL SNPs predicting ANKLE1 expression in breast tissue that were associated with breast cancer; both have been previously associated with breast cancer risk." (PMID 28362817, 2017). "Both cis-eQTLs for ANKLE1, rs8170 and rs34084277, among several other SNPs in the 19p13.11 region, have been identified as breast cancer risk variants in several GWAS." (PMID 28362817, 2017). "In our study, we found that higher expression levels of ANKLE1 were associated with an increased risk of breast cancer." (PMID 28362817, 2017). "The association between ER- breast cancer and seven 1000 Genomes variants passed study-wide significance, including the GWAS-discovered variant rs10069690 and six variants in ANKLE1-BABAM1 locus." (PMID 27825120, 2016). "The expression level of AFAP1L2, involved in signal transduction, has been described as a potential tumor marker in soft tissue tumors, while endonuclease-encoding ANKLE1, which plays a role in DNA damage and repair, has been suggested as a breast cancer marker." (PMID 35408779, 2022). "Recent research using whole exome sequencing of breast cancer samples further indicated that mutation of ANKLE1 may contribute to the susceptibility to breast cancer." (PMID 34055803, 2021). "Our results suggest that an ancestry-specific Duffy-null allele and differential prevalence of a polymorphic gene variant of ANKLE1 may play a role in TNBC breast cancer outcomes." (PMID 33927264, 2021).
breast carcinoma (continued). "The variant rs2363956 of the ANKLE-1 gene has been previously reported to be associated with breast cancer risk in Chinese population, however its role in the population under study remains ambiguous since only variants with call rate over 90% were acknowledged in this study." (PMID 32894086, 2020). "Moreover, ANKLE1 ectopic expression is linked to breast cancer risk." (PMID 40493412, 2025). "Likewise, the fact that spheroids formed by normal breast epithelium cells after ANKLE1 expression exhibit precancerous phenotypes is supportive of the model that breast cancer risk attributed by ANKLE1 expression is mediated through ANKLE1’s effect on mitochondria biology." (PMID 36859531, 2023). "The effect of these polymorphisms on Ankle1 function remains to be explored, but our finding that lem-3; brc-1 double mutants show elevated sensitivity to DNA damage is consistent with Ankle1 being the most likely gene in 19p13.1 to affect breast cancer disposition." (PMID 29463814, 2018). "Therefore, higher expression of ANKLE1 is associated with increased breast cancer risk." (PMID 28957321, 2017). "We integrated the most recent meta-analysis of breast cancer GWAS10 and Genotype-Tissue Expression (GTEx) project data; we found that ANKLE1 eQTL variants colocalize with the cancer susceptibility GWAS variants." (PMID 36859531, 2023). "Just as ANKLE1 is more highly expressed in TNBC cancers and the effect size for the breast cancer GWAS is amplified in TNBCs, the association between mtDNA-CN and breast cancer risk effect size is unique to the TNBC subtype." (PMID 36859531, 2023). "If ANKLE1 digests mtDNA in these cells, we expect that mtDNA content in breast cancer is inversely correlated with ANKLE1 expression." (PMID 36859531, 2023). "ANKLE1 (ankyrin repeat and LEM domain) is involved in DNA damage response and DNA repair and is associated with breast cancer development." (PMID 35676660, 2022). "We found that survival trends in TCGA breast cancer cases are significantly impacted by ANKLE1 expression, but that the advantage of ANKLE1 expression only benefits EA patients." (PMID 33927264, 2021). "To investigate the contribution of ANKLE1 gene in DNA repair in relation to breast cancer we assessed the expression levels under different exposure time intervals." (PMID 33584808, 2020). "ANKLE1 (i.e., ankyrin repeat and LEM domain containing 1) has been previously implicated in breast cancer." (PMID 28362817, 2017). "LEM-3 acts cooperatively with BRC-1-BRD-1 to promote genome integrity, which might provide a molecular basis for the suspected role of ANKLE1 in human breast cancer." (PMID 35137093, 2022). "Given the key role of ANKLE1 in breast cancer, we speculated that ANKLE1 might be localized near the nuclear membrane considering its shuttling property inside the cytoplasm and nucleus." (PMID 33584808, 2020). "In trans-ethnic meta-analyses of U4C and UK Biobank data, we found significant associations between breast cancer risk and the expression of RCCD1 (joint p-value: 3.6x10-06) and DHODH (p-value: 7.1x10-06) in breast tissue, as well as a suggestive association for ANKLE1 (p-value: 9.3x10-05)." (PMID 28362817, 2017). "While genome-wide association studies (GWAS) have implicated RCCD1 and ANKLE1 in breast cancer risk, they have not identified the remaining three genes." (PMID 28362817, 2017).
breast carcinoma (continued). "Therefore, we prioritized SNPs within GWAS loci that are predicted to affect transcription factor binding and module expression of ANKLE1 and ZNF404 to confer breast cancer risk." (PMID 28957321, 2017). "While RCCD1 and ANKLE1 have been implicated by GWAS of breast cancer risk, DHODH has not been previously identified." (PMID 28362817, 2017). "Detailed studies on ANKLE1 involvement in breast cancer for Indian population are unknown." (PMID 33584808, 2020). "ANKLE1 is more highly expressed in triple negative breast cancers (TNBC) compared to adjacent normal tissue and other breast cancer subtypes." (PMID 36859531, 2023). "ANKLE1 gene be further validated and exploited for developing a novel approach toward breast cancer diagnosis and treatment." (PMID 33584808, 2020). "We also found some support for an association between breast cancer risk and eQTL for ACAP1 (EUGENE P = 0.003) and ANKLE1 (EUGENE P = 0.01), but not for DHODH (best sentinel eQTL P = 0.119)." (PMID 30988301, 2019).
ovarian carcinoma (8 papers, 2015 to 2023). A malignant neoplasm originating from the surface ovarian epithelium. "Alleles that are associated with increased risk of breast and ovarian cancer are associated with high expression of ANKLE1." (PMID 36859531, 2023). "This work suggested that ANKLE1 was the most likely the casual gene within the chr19p13.1 breast and ovarian cancer susceptibility locus." (PMID 36859531, 2023). "Several studies have implicated the mutations in ANKLE1 gene to the development of breast and ovarian cancers indication its role in the DNA damage repair process." (PMID 33584808, 2020). "Recent studies have indicated toward an increased predisposition to breast and ovarian cancer with small nucleotide polymorphisms in the human ANKLE1 gene." (PMID 33584808, 2020). "Small nucleotide polymorphisms within the human Ankle1 gene have been associated with increased risk for certain forms of breast and ovarian cancer." (PMID 27010503, 2016). "Altogether, these data suggest that multiple SNPs at 19p13 regulate ABHD8 and perhaps ANKLE1 expression, and indicate common mechanisms underlying breast and ovarian cancer risk." (PMID 27601076, 2016). "That SNPs in the 19p13.11 locus have also been implicated in ovarian cancer implies that ANKLE1 may also be involved in hormonally-mediated carcinogenic pathways." (PMID 28362817, 2017). "The expression of ANKLE1 in breast epithelial cells and its presence in ovarian cancer indicated that ANKLE1 might be regulating women cancers through hormonal mechanisms." (PMID 33584808, 2020).
colorectal cancer (3 papers, 2021 to 2024). A primary or metastatic malignant neoplasm that affects the colon or rectum. "ANKLE1 has also been indicated as a potential colorectal cancer susceptibility gene." (PMID 34055803, 2021). "The expression level of ANKLE1 is lower in colorectal cancer tumors compared with normal tissues." (PMID 34055803, 2021). "Furthermore, future studies on ANKLE1 and its interaction network may have clinical implications in breast, ovarian and colorectal cancers." (PMID 34055803, 2021). "YTHDF1 also enhances the transcriptional efficiency of ANKLE1 however it does not maintain ANKLE1 mRNA stability, via recognition of 6A modification thus acting as a tumor suppressor and playing a crucial role in the inhibition of colorectal cancer cell proliferation." (PMID 36650570, 2023).
Autoimmunity (2 papers, 2015 to 2023). The occurrence of an immune reaction against the organism's own cells or tissues. "It is therefore proposed that ANKLE1 prevents DNA damage and autoimmunity by cleaving chromatin bridges to avoid catastrophic breakage mediated by actomyosin contractile forces." (PMID 36825683, 2023).
triple-negative breast carcinoma (2 papers, 2023). An invasive breast carcinoma which is negative for expression of estrogen receptor (ER), progesterone receptor (PR), and human epidermal growth factor receptor 2 (HER2). "Several cases of m6A methylated modification in cancer have been reported in the literature, and it is clear that the variant rs8100241 located in ANKLE1 was significantly associated with susceptibility of BRCA1 mutation triple negative breast cancer." (PMID 37194014, 2023).
diabetic retinopathy (1 paper, 2023). "We did not see an association for the APOL1 and ANKLE1/PLVAP SNPs with baseline Diabetic Retinopathy Severity Score (DRSS) (N = 1,168; P>0.1)." (PMID 37585454, 2023).
non-small cell lung carcinoma (1 paper, 2021). A group of at least three distinct histological types of lung cancer, including non-small cell squamous cell carcinoma, adenocarcinoma, and large cell carcinoma. "Most intriguingly, one study in non-small-cell lung cancer indicated the combination of ANKLE1 RNAi with paclitaxel increased the efficacy of the drug response." (PMID 33927264, 2021).
osteosarcoma (1 paper, 2016). A usually aggressive malignant bone-forming mesenchymal neoplasm, predominantly affecting adolescents and young adults.
prostate tumor (1 paper, 2022). "We also further validated the mRNA and protein expression levels of ANKLE1, EMD, and LEMD2 in human prostate tumor specimens by qPCR, WB, and IHC." (PMID 35650630, 2022). "In addition, we also further validated the mRNA and protein expression levels of ANKLE1, EMD, and LEMD2 in human prostate tumor specimens by qPCR, WB, and IHC." (PMID 35650630, 2022). "Furthermore, we also validated the mRNA and protein expression levels of ANKLE1, EMD, and LEMD2 in human prostate tumor specimens by qPCR, WB, and IHC." (PMID 35650630, 2022).
psoriasis (1 paper, 2017). An autoimmune condition characterized by red, well-delineated plaques with silvery scales that are usually on the extensor surfaces and scalp. "The four genetic variants—rs1802073 G>T in SFRP4, rs1105223T>C in CRB2, rs3821414T>C in ARHGEF3, rs11086065A>G in ANKLE1—could be validated as predictive markers for the response to acitretin in psoriasis." (PMID 28146080, 2017).
ZIKV infection (1 paper, 2025). "Conversely, we found that the localization of GFP and ANKLE1 did not change following ZIKV infection." (PMID 39804047, 2025).
cancer (13 papers, 2014 to 2023). A tumor composed of atypical neoplastic, often pleomorphic cells that invade other tissues. "Although we do not claim to identify the causal variant(s) that lead to increased cancer risk, these analyses confirm that ANKLE1 is the most likely causal gene within the region." (PMID 36859531, 2023). "Little experimental evidence exists regarding associations between over- or under-expression of ANKLE1 and cancer risk." (PMID 28362817, 2017). "A recent study presented a potential linkage of SNPs in the human ANKLE1 gene, showing an association between a function of ANKLE1 in multiple autoimmune syndromes and the increased risk of certain cancers." (PMID 28146080, 2017). "Seven of the 13 candidate causal SNPs in Peak 1 resided either in the ANKLE1 promoter or in putative regulatory elements (PREs-A-C) in breast and ovarian normal and cancer cell lines." (PMID 27601076, 2016). "The cancer-linked polymorphism in human ANKLE1 is located in its Ankyrin repeats, which are common protein-protein interaction motifs." (PMID 27010503, 2016). "Cells overexpressing ANKLE1 showed a significant enrichment for cancer-associated and cell growth/proliferation pathways in both breast (P=3.36 × 10−6) and ovarian (P=2.43 × 10−27) epithelial cells." (PMID 27601076, 2016). "A previous study reported that METTL3-mediated m6A modification of ankyrin repeat and LEM domain containing 1 (ANKLE1) acted as a cancer regulator mediated CRC cell growth and maintained genomic stability." (PMID 37370759, 2023). "We suggest that ANKLE1-induced degradation of the mitochondria facilitates the Warburg effect to promote cancer growth." (PMID 36859531, 2023). "Nevertheless, research on ANKLE1 needs further attention due to the link to human cancer development." (PMID 27010503, 2016). "Since ANKLE1 has been a player before in some cancers, further intensive study could be done to investigate the role of ANKLE1 and its potential role in DNA repair mechanism in various cancers." (PMID 33584808, 2020). "The ANKLE1 gene offers a magnanimous prospect in the cancer therapeutics." (PMID 33584808, 2020). "ANKLE1-induced mitophagy may also promote survival of cancer cells by avoiding apoptosis." (PMID 36859531, 2023). "The short lifespan of mice compared to man may also contribute to the fact that Ankle1-deficient mice are not prone to cancer." (PMID 27010503, 2016). "In addition, ANKLE1 has been repeatedly shown to be involved in DNA repair pathways in preclinical and in vitro screens, including endonuclease activity, proliferation, and drug response in CRISPR screens of cancer cell lines." (PMID 35676660, 2022).
tumor (8 papers, 2020 to 2023). "Using data from the HPA database, we found immunohistochemical images of five prognostic signature genes in normal and tumor tissues, including three upregulated genes (ANKLE1, PPP1R27, and AMH) and two downregulated genes (FLRT3 and PPBP)." (PMID 35676660, 2022). "Taken together, all of these results strongly implicated that ANKLE1, EMD, and LEMD2 could serve as major tumor immune infiltration regulators in PRAD." (PMID 35650630, 2022). "Knockdown of ANKLE1 leads to increased cell proliferation and formation of micronucleated cells, suggesting that ANKLE1 could act as a tumor suppressor by maintaining genomic stability." (PMID 34055803, 2021). "Thus ANKLE1 poses to be a promising candidate to explore for curtailing the extensive spread of the neoplastic disease." (PMID 33584808, 2020). "For LEMs, ANKLE1 may control tumor development via DNA damage and repair process." (PMID 35650630, 2022). "Among all LEMs, only the expressions of ANKLE1, EMD, and LEMD2 were correlated with advanced tumor stage and survival prognosis in PRAD." (PMID 35650630, 2022). "Furthermore, we used TISIDB, TIMER, and UCSC Xena databases to investigate the correlation between ANKLE1, EMD, and LEMD2 expressions and tumor-infiltrated immune cells in the tumor microenvironment." (PMID 35650630, 2022). "This study further found a new mechanism that ANKLE1, EMD, and LEMD2 expressions may affect the prognosis of PRAD through tumor immune infiltration." (PMID 35650630, 2022). "In addition, we examined the prognostic value of ANKLE1, EMD, and LEMD2 levels and tumor-infiltrating resting NK cells in PRAD, using the Cox proportional hazard model by TIMER." (PMID 35650630, 2022).
ANKLE1 also shares sentences with these, for which no sentence is quoted: infection (3 papers); epithelial ovarian tumors (1); Fanconi anemia (1); fungal infections (1); Hyperglycemia (1); soft tissue tumors (1).